IL6 (interleukin 6)
Diseases named in the same sentence as IL6 in open-access papers (continued):
Sharing a sentence is not in itself a finding about the gene and the disease.
bacterial infection (continued). "In addition, STAT3 is involved in regulating the body’s response to viral and bacterial infections since the interaction of IL-6 and IL-10 with their respective receptors triggers the phosphorylation process of STAT3." (PMID 35327350, 2022). "Differentiation of G-/G+ bacterial infections with IL-6 combined with IL-10." (PMID 35432366, 2022). "Therefore, this study believes that the levels of IL-6 and IL-10 can roughly determine G-/G+ bacterial infection." (PMID 35432366, 2022). "We emphasized the importance of IL-6 and IL-8 in bacterial infections." (PMID 35463642, 2022). "On the other hand, triggered by viral or bacterial infections, the production of TNFα, IL-6, IL-1β, and INFγ may amplify the ER stress in many cell types including macrophages, pancreatic β cells and hepatocytes." (PMID 34834808, 2021). "However, his hospital stay was further complicated by decreasing oxygen saturation and rising inflammatory markers including procalcitonin and IL-6, suggesting superimposed bacterial infection." (PMID 35036190, 2021). "We used LPS to establish a human keratinocyte (HaCat) bacterial infection and inflammation model to investigate whether Muse cell supernatant could downregulate the inflammatory factors IL-17α, IL-6 and IL, as shown in the in vivo experiment." (PMID 34930455, 2021). "Furthermore, we found that 88.89% (200/225) of patients with IL-6 ≥34.12 pg/ml had a bacterial infection in their lungs." (PMID 34925324, 2021). "Different findings by different authors also highlight another central problem with the use of IL-6 as a marker for bacterial infections in the context of acute SAH besides timing, i.e., the prominent role of IL-6 signaling in both bacterial and aseptic inflammatory conditions, which often coexist." (PMID 33923626, 2021). "It should be noted that the abnormal increase of IL-6, IL-8 and IL-10 in patients with hematological malignancies may not only occur when bacterial infections in the lungs occur." (PMID 34925324, 2021). "Furthermore, elevated levels of IL-6 are also seen during viral and bacterial infections, physical exercise, and oxidative stress." (PMID 33868439, 2021). "Since cytokines released by monocytes pivotally determine survival during bacterial infections, we analysed induction of IL-6, IL-1beta and TNF-alpha separately in TLR-stimulated classical CD14++CD16−, intermediate CD14++CD16+ and non-classical CD14+CD16++ monocytes." (PMID 33278000, 2021). "Systemic PCT production is triggered by bacterial toxins (endotoxin) and by pro-inflammatory cytokines such as tumor necrosis factor (TNF)-α, interleukin-1-β (IL-1β), and interleukin-6 (IL-6) as an immunological danger signal able to alert the host of a possible bacterial infection." (PMID 34195086, 2021). "Similarly, to these results, we demonstrated that IL-6 was the only biomarker significantly related to the presence of a systemic response and bacterial infection, both quantitatively and qualitatively (cut-off point > 85 pg/mL)." (PMID 34828740, 2021). "In a recent report, salivary IL-6 levels could predict bacterial infection in premature neonates with high sensitivity and specificity." (PMID 34708133, 2021). "This phenomenon is probably because, usually, the level of procalcitonin increases in the presence of cytokines, caused by a bacterial infection (IL-1b, TNF-a, and IL-6), and its production is regulated by the signal transducer and activator of transcription 3 (STAT-3)." (PMID 34439009, 2021). "Furthermore, lipopolysaccharide-induced TLR4 signaling cascades were shown to repress the expression of the let-7 family and rescue cytokine production of IL-6 and IL-10, both of which are critical in bacterial infection." (PMID 33805523, 2021). "In adult patients with hematological malignancies with bacterial infection of the lungs, as an anti-inflammatory factor, the increase of IL-10 may be to inhibit the high expression of the pro-inflammatory factors IL-6 and IL-8." (PMID 34925324, 2021).
bacterial infection (continued). "Interestingly, taurine and malate alleviated the expression of Cox-2, IL-1β, IL-6, IL-8, and elevated the expression of C3 after bacterial infection." (PMID 32316833, 2020). "Suppression of the interferon or other mediators (e.g., IL-6) may also mediate the development of the secondary bacterial infection along with the immune suppression." (PMID 32722596, 2020). "Immune responses that may contribute to clearance of bacterial infection in general (increased IL-6, IL-8 and MIP-3α) were detected when acquiring NG but were only statistically significant in no-HC users." (PMID 31914129, 2020). "Macrophages polarize to M1 response to kill the invading pathogens (such as Salmonella typhi, Salmonella typhimurium, and Mycobacterium tuberculosis, etc.)by the production of various proinflammatory cytokines including TNF-α, IL-6, and IL-1β in the early stage of bacterial infection." (PMID 33585271, 2020). "Furthermore, this result confirms extensive previous studies showing that IL-6 modulates the accumulation of neutrophils during bacterial infections and inflammation." (PMID 33322581, 2020). "Whether IL-6 regulation by TLT2 described here also occurs in other bacterial infection remains unknown." (PMID 33042115, 2020). "Similar, Cochlin, secreted from follicular dendritic cells in the spleen, was crucial for systemic immune response against bacterial infection by induces secretion of cytokines (IL-1βand IL-6) and enhances the recruitment of immune cells (neutrophils and macrophages)." (PMID 33281116, 2020). "As with IL-6 induction, the data suggests that the hCMECs respond in a higher degree to bacterial endotoxins released by bacterial clearance following phage therapy that the actual bacterial infection itself." (PMID 32483257, 2020). "As such, increased IL6 has been shown to be protective against bacterial infection." (PMID 30795743, 2019). "The production of a number of cytokines by matured monocytes, such as tumor necrosis factor-alpha (TNF-alpha) and IL-6, plays an important role in the initiation of the acquired immune response, creating an inflammatory environment favorable for fighting a bacterial infection." (PMID 31027390, 2019). "TNF-α and IL-6 are typical pro-inflammatory cytokines and have been used as potential markers for ongoing bacterial infections in piglets, while IL-22 is essential for maintaining mucosal barrier homeostasis against specific pathogens by eliciting innate defense response." (PMID 31286936, 2019). "Over the past 30 years, a wealth of data generated from ex vivo and in vivo investigations have supported IL-6 is a pleiotropic cytokine and a major player in integrated immunity via its role in defense against viral, parasitic, fungal and bacterial infections." (PMID 32038632, 2019). "Bacterial infection introduces the secretion of IL-6 and IL-8." (PMID 31551961, 2019). "Proinflammatory cytokines (such as IL-6 and TNF-α) play an important role in the regulation of enteric pathogenic bacteria and the concentration of these cytokines in the serum of animals is usually increased after enteric pathogenic bacterial infection." (PMID 31126046, 2019). "In addition, IL-6 mediated increased surface expression of MARCO on macrophage enhancing their phagocytic capacity during secondary bacterial infection." (PMID 32038632, 2019). "However, treatment with resveratrol did not change the levels CCL2 and IL-12p70 or slightly changed the levels of IL-6, upon bacterial infection." (PMID 30971927, 2019). "In addition, IL-6 has been shown to improve bacterial phagocytosis by up-regulating MARCO surface expression in macrophages during secondary bacterial infection." (PMID 32038632, 2019). "Furthermore, macrophages produce a large variety of cytokines, including tumor necrosis factor-α, interferon-β, and interleukin-6 following pathogen engulfment, and these cytokines activate both innate and adaptive immune responses to bacterial infection." (PMID 29942306, 2018).
bacterial infection (continued). "IL-6 is an important mediator of the host response to injury and bacterial infection." (PMID 30142971, 2018). "Furthermore, the expression and secretion of TNF-α and IL-6 in gingival tissue was significantly decreased in LG2055-administered mice after bacterial infection." (PMID 28373699, 2017). "Although TNF secretion was similar to the control group, IL-6 and IFN-γ production remained low and could possibly explain the susceptibility of SS patients to bacterial infection." (PMID 27780938, 2016). "Bacterial infections lead to NFκB activation via Toll-like receptors in airway epithelial cells and alveolar macrophages or dendritic cells, which in turn induce transcription of pro-inflammatory cytokines such as IL-6 and IL8." (PMID 24885494, 2014). "However, for the patients with bacterial infection, there was positive correlation of the serum IL-6 levels with age (r = 0.479; P = 0.069) and duration of fever before admission to the hospital (r = 0.5; P = 0.056)." (PMID 23690657, 2013). "In addition, increased TNF-α and IL-6 production can potentiate the severity of combined influenza A virus and bacterial infections." (PMID 24191131, 2013). "On the other hand, IL-6 is also related to the development of bacterial infections." (PMID 23936360, 2013). "Bacterial infection could be another case for IL-6 induction, because we found plaque of streptococcus in the inflamed skin area of some, but not all, Socs3 cKO mice (data not shown)." (PMID 22792286, 2012). "The value of PCT in febrile neutropenia may be as part of a combination with other biomarkers of bacterial infection such as IL-6 and IL-8 as shown in a small study of pediatric patients with febrile neutropenia." (PMID 21936959, 2011). "Nevertheless, we cannot exclude that CRP production is increased in these patients by bacterial infections that could also favor IL-6 production." (PMID 22032643, 2011). "TNF-α and IL-6 are important for the early innate immune response in bacterial infection." (PMID 21818362, 2011). "Furthermore, a previous report showed that human PYCARD is required for TNFα and IL-6 expression upon bacterial infection." (PMID 20808838, 2010). "IL-6, mainly produced by cells such as Th2 cells, monocytes, B cells and muscle tissue, is often regarded as a useful biomarker of bacterial infections in pigs, and has been reported to be present for several days after an Actinobacillus pleuropneumoniae infection." (PMID 18700003, 2008). "We measured the inflammatory cytokine IL-6 in mouse serum after bacterial infection." (PMID 18523661, 2008). "Notably, the loss of CaMKKβ activity inhibited the ability of tilapia leukocytes to express Perforin A, Granzyme B, IFN-γ, TNF-α, and IL-6 and reduced the frequency of Granzyme B-producing T cells, consequently impairing the ability to control bacterial infection." (PMID 41249580, 2025). "IL-6 has proven to be a valuable biomarker in guiding therapeutic decisions, particularly regarding the initiation, type, and duration of antibiotic treatment: Elevated IL-6 levels at hospital admission may reflect an active systemic inflammatory response due to bacterial infection." (PMID 40806991, 2025). "IL-1β, IL-6, IL-18, and tumor necrosis factor (TNF)-α are pro inflammatory cytokines, and procalcitonin (PCT) and C-reactive protein (CRP) are nonspecific markers of systemic inflammation that increase sharply during pathogenic infections including bacterial infections." (PMID 40532039, 2025). "In addition to SP’s immune-stimulating effects, O. niloticu’s survival following bacterial infection can also be a result of its anti-inflammatory abilities, as demonstrated by an increase in the levels of the cytokine IL6, which is a strong pro-inflammatory cytokine." (PMID 37563419, 2024). "Besides TNF-α and IL-6, also IL-1β drives protective immunity during bacterial infections." (PMID 38562936, 2024).
bacterial infection (continued). "Indeed, previous literature shows that genetic polymorphisms in innate immune signaling factors, such as IL-6, TLR2 and IL-1β may explain the variation in disease severity during bacterial infections in preterm and term newborns." (PMID 38562936, 2024). "Reductions in proinflammatory markers C-Reactive protein (CRP), interleukin – 6 (IL6) and tumor necrosis factor-α (TNFα) and increments in anti-inflammatory markers (interleukin – 4 (IL4)) were associated with an improvement in CSDD and MSEE in patients recovering from a bacterial infection." (PMID 37762523, 2023). "Furthermore, IL-6, an essential pro-inflammatory cytokine produced by macrophages, contributes to acute immune responses, while IL-1β plays a vital role in initiating and intensifying inflammatory responses to bacterial infections." (PMID 37627631, 2023). "In addition, we tested whether conventional inflammation biomarkers (e.g., CRP, PCT, IL-6) could effectively identify and predict bacterial infections during the 28-day observation period in patients following liver transplantation." (PMID 35883545, 2022). "Although overall mechanisms remain elusive, it is known that bacterial infections activate NF-kB pathway via toll-like receptors and airway epithelial cells, which, in turn, promotes transcription of pro-inflammatory substances like IL-6, IL-8, and interferon gamma (IFN-γ)." (PMID 36466839, 2022). "Indeed, we would speculate that the IL-6 response detected in the spleen is reflective of the natural response to bacterial infection at other tissue sites, including the reproductive tract." (PMID 32487756, 2020). "Furthermore, IL-6-dependent reduction of IFN-γ was also described for other bacterial infections." (PMID 33322581, 2020). "For IL-6, it has been shown that classic signaling has rather anti-inflammatory properties, for example, via induction of the synthesis of acute-phase proteins in hepatocytes to combat bacterial infections, or as an important factor to induce liver regeneration." (PMID 27493449, 2016). "Therefore, cytokines such as TNF-α and IL-6 could work in synergy to maintain olfactory tissue homeostasis while removing the bacterial infection." (PMID 22642871, 2012). "Therefore, during bacterial infections, a hallmark of CF, mast cells could via TLR receptors act as a source of IL-6 and other pro-inflammatory cytokines such as IL-1, IL-8, and GRO-α." (PMID 22014187, 2011). "HnRNPs regulate innate as well as adaptive immunity in response to bacterial infections such as HnPNPA0 binds to specific sequence of inflammatory genes including TNF-α and IL-6, controlling the inflammatory response." (PMID 41026719, 2025). "The inflammatory parameters—particularly IL-6 and PCT—were substantially higher at ICU admission among patients with bacterial infection." (PMID 41472286, 2025). "Anaerobic bacterial infections induce local and systemic increases of proinflammatory cytokines including TNF-α, IL-1β, and IL-6." (PMID 40552326, 2025). "Intramuscular iron supplementation alleviated the clinical symptoms of bacterial infection, decreasing the diarrhea rate by 53% and mitigating the inflammatory response with lower serum levels of pro-inflammatory cytokines, such as TNF-α, IL-6, and IL-8." (PMID 40746956, 2025). "For example, bacterial infections induce inflammation through recognition by dedicated PRRs as well as through virulence factors resulting in high levels of TNF‐α, IL‐6 and acute phase response proteins." (PMID 36800487, 2025). "Bacterial infection led to a significant increase in the levels of pro-inflammatory factors, such as TNF-α, Il-1ꞵ, and IL-6, while the level of the anti-inflammatory factor IL-10 decreased." (PMID 40713896, 2025). "The data presented in this study suggests intricate immune modulation of macrophage responses to bacterial infections, particularly in relation to TNF-α, IL-6, IL-10, and IL-12A cytokine profiles." (PMID 40873569, 2025).
bacterial infection (continued). "Delayed wound healing can be attributed to a widespread inflammatory response primarily driven by bacterial infection, leading to failed macrophage polarization and excessive secretion of inflammatory factors such as TNF-α, IL-6, and IL-1β." (PMID 40051835, 2025). "Administration of the AdipoR1 antibody during bacterial infection impaired the inducible expression of cytotoxic genes Perforin A and Granzyme B and pro-inflammatory cytokines IFN-γ, TNF-α, and IL-6 and reduced the ability of T cells to produce Granzyme B." (PMID 41249580, 2025). "Bacterial infection induces endotoxin production, which stimulates macrophages to produce high levels of pro-inflammatory cytokines, including TNF-α, IL-6, and IL-1β." (PMID 39625293, 2025). "On the other hand, NR2C2 is recognized for its proinflammatory effects during bacterial infections as it augments NFkB expression, thereby fostering the production of IL1B and IL6 in macrophages." (PMID 41516283, 2025). "Following a mixed bacterial infection, the experimental groups showed significantly higher levels of NFκB, TLR4, IL-6, TNF-α, and IL-1β compared to the control group (p < 0.05)." (PMID 40136393, 2025). "The intensities of inflammatory indicators, like IL-1β, IL-6, and TNF-α, usually rise during bacterial infections as they are part of bacterial pathogenesis." (PMID 39338376, 2024). "The NET-array device developed and validated in this study, enabled the quantification of increased NET release to Pseudomonas aeruginosa PAO1 bacterial infection in microenvironments rich in inflammatory cytokines, TNF-α and IL-6." (PMID 38189525, 2024). "Activation of TLR2/4 can induce NF-κB-regulated inflammatory cytokines, such as interleukin 6 (IL-6) and tumor necrosis factor-alpha (TNF-α) during bacterial infection." (PMID 38182816, 2024). "IL-6 and TNF-α are inflammatory markers frequently produced in response to tissue injury and bacterial infections." (PMID 39415253, 2024). "It is known that, in patients with bacterial infection, PCT blood levels increase in response to toxins and some cytokines (TNF-α, IL-6, IL-1β), and its level decreases dramatically in parallel with the success of the treatment." (PMID 39797227, 2024). "Investigating potential biomarkers, IL-6 and C-reactive protein (CRP) were scrutinized, alongside PCT, which emerged as another biomarker due to its elevation in bacterial infections." (PMID 39768616, 2024). "Preadipocytes respond to bacterial infections by producing and releasing proinflammatory cytokines such as TNF-α, IL-6, and IL-8, which trigger inflammation and attract immune cells to the affected area." (PMID 38111581, 2023). "In our study, compared with healthy pregnant women, we observed a significant increase in IL‐2, IL‐6, IL‐10 and IFN‐γ in pregnant women with both influenza A and bacterial infection but lower levels of TNF‐α in both groups." (PMID 37638092, 2023). "The significant association between NE-WY/NE-SFL, which reflect the immune response in neutrophils, and IL-6/PCT, suggests potential benefits in the use of a combination of these biomarkers in predicting severe bacterial infections." (PMID 37324133, 2023). "Studies have indicated that procalcitonin values of 1 μg/L or higher show better specificity, sensitivity, and predictive value for distinguishing viral from bacterial infections in children compared to CRP, interleukin 6, or interferon-alpha." (PMID 37600437, 2023). "Serum CRP and IL-6 levels are generally increased when bacteria, viruses, fungi, and other pathogens are infected, and high PCT levels usually indicate bacterial infection." (PMID 38322760, 2023). "Similar to our findings, the levels of pro-inflammatory cytokines, IL-6, TNF-α, and IL-1β, tested after bacteriophage administration, were significantly lower than in the group with developed bacterial infection, treated with PBS alone." (PMID 36211337, 2022).